SLC39A12 (solute carrier family 39 member 12)
Description:
Uniporter that promotes Zn(2+) import from the extracellular space to the cytoplasm across the cell membrane. The transport activity is temperature dependent. May play a role in neurulation and neurite extension. May play a key role in maintaining intracellular zinc content at levels that reduce the inhibitory effects of rises in oxidative stress on spermatogonia and spermatozoa viability during spermatogenesis.
Synonyms: LZT-Hs8; ZIP-12; ZIP12; FLJ30499; bA570F3.1
Tractability: Antibody: UniProt predicts a signal peptide or a membrane-spanning region; its Gene Ontology location is reachable by antibodies, with medium confidence. PROTAC: its protein half-life has been measured.
Gene: Protein-coding gene on chromosome 10 (17,951,839 to 18,043,292, forward strand). Ensembl gene ENSG00000148482.
Subcellular location: Membrane
Gene Ontology:
Molecular function: monoatomic cation:bicarbonate symporter activity; zinc ion transmembrane transporter activity; metal ion transmembrane transporter activity
Biological process: intracellular monoatomic cation homeostasis; neural tube formation; neuron projection extension; zinc ion import across plasma membrane; bicarbonate transport; metal ion transport; transmembrane transport
Cellular component: extracellular vesicle; membrane; plasma membrane
Genetic constraint (gnomAD): Loss-of-function variants: 59 observed, 66.03 expected, observed/expected ratio (o/e) 0.89, 90% interval 0.72 to 1.11. The upper end of that interval is the gene's LOEUF score, 1.11, which puts it in group 4 of 6, group 1 being the genes least tolerant of losing a copy. Missense variants: 831 observed, 790.57 expected, observed/expected ratio (o/e) 1.05, 90% interval 0.99 to 1.11. Synonymous variants: 327 observed, 289.97 expected, observed/expected ratio (o/e) 1.13, 90% interval 1.03 to 1.24.
Homologues: Orthologues: chimpanzee SLC39A12 (99% identical), macaque SLC39A12 (97% identical), dog SLC39A12 (84% identical), pig SLC39A12 (83% identical), rabbit SLC39A12 (83% identical), guinea pig SLC39A12 (79% identical), mouse Slc39a12 (78% identical), rat Slc39a12 (71% identical), tropical clawed frog slc39a12 (52% identical), Drosophila melanogaster Zip71B (18% identical), Caenorhabditis elegans zipt-15 (14% identical). Paralogues in human: SLC39A4 (30% identical), SLC39A10 (23% identical), SLC39A6 (20% identical), SLC39A14 (20% identical), SLC39A5 (19% identical), SLC39A8 (19% identical).
Diseases named in the same sentence as SLC39A12 in open-access papers:
SLC39A12 is named in the same sentence as 27 diseases in open-access papers, as found by Europe PMC text mining. Sharing a sentence is not in itself a finding about the gene and the disease. The quoted sentences say what the papers report.
pulmonary hypertension (6 papers, 2017 to 2023). Increased pressure within the pulmonary circulation due to lung or heart disorder. "In addition, in CHH-exposed rats with an alteration in the Slc39a12 gene, which codes for this transporter, decreased Zn2+i levels were evident and attenuated the development of pulmonary hypertension." (PMID 35805984, 2022). "Interestingly, the zinc transporter SLC39A12 was reported to serve as a major regulator of pulmonary vascular remodelling under low-oxygen conditions, as genetically deleting Slc39a12 expression protected against the development of pulmonary hypertension in rats housed in a hypoxic atmosphere." (PMID 33081634, 2020).
schizophrenia (6 papers, 2016 to 2023). A major psychotic disorder characterized by abnormalities in the perception or expression of reality. "This study extends our expression array findings by showing that mRNA for SLC39A12 variant 1 and 2 are higher in BA 8, 9 and 44 from subjects with schizophrenia." (PMID 27336053, 2016). "Lastly, it is interesting to note that SLC39A12 was recently identified as a strong candidate gene for ASD and schizophrenia susceptibility, as reviewed by Davis, underscoring the need for additional study of ZIP12’s potential pathological roles, especially in the CNS." (PMID 35745255, 2022). "Considering the reports of dysregulation of SLC39A12 in persons with schizophrenia, this suggests that the putative dysregulation of zinc processing in schizophrenia may be associated with astrocytes." (PMID 29892006, 2018). "Our expression microarray studies showed messenger RNA (mRNA) for solute carrier family 39 (zinc transporter), member 12 (SLC39A12) was higher in dorsolateral prefrontal cortex from subjects with schizophrenia (Sz) in comparison with controls." (PMID 27336053, 2016). "Our data from the human cortex adds to our expression array studies in showing that SLC39A12 mRNA levels are higher in schizophrenia." (PMID 27336053, 2016). "However, overall our data are consistent with the conclusion that there are widespread increases in the expression of SLC39A12 in the cortex from subjects with schizophrenia some of which are limited to the cortex from subjects with MRDS." (PMID 27336053, 2016). "To gain the data on whether changes in SLC39A12 expression might be specific to schizophrenia we measured levels of mRNA for the gene in BA 9 from subjects with major depressive disorder (MDD) and bipolar disorder (BD)." (PMID 27336053, 2016). "As increased levels of murine Slc39a12 mRNA has been shown to correlate with increasing cellular zinc uptake, our data would be consistent with the possibility of a dysregulated zinc homeostasis in the cortex of subjects with schizophrenia due to altered expression of SLC39A12." (PMID 27336053, 2016). "If, like SLC39A12, changes in other ZnT prove to be limited to subjects with schizophrenia and widespread throughout the cortex, then the combined effect of these changes could have substantial effects on Zn homeostasis and this could be a factor contributing to the pathophysiology of the disorder." (PMID 27336053, 2016). "Our current data also argue that changes in cortical levels of SLC39A12 in schizophrenia are not simply due to antipsychotic drug treatment." (PMID 27336053, 2016).
Alzheimer disease (2 papers, 2022 to 2024). A progressive, neurodegenerative disease characterized by loss of function and death of nerve cells in several areas of the brain leading to loss of cognitive function such as memory and language. "In addition, by overlaying the cRE–gene covariability map and TF binding motif data along the genome axis, we revealed a potential cis-regulatory relationship of pathogenic genes specific to AST4, such as SLC39A12, in neurodegenerative diseases such as Alzheimer's disease." (PMID 38091510, 2022).
breast carcinoma (1 paper, 2021). "Our findings were consistent with those of the previous study, in that high mRNA expression levels of SLC39A6 and SLC39A14 indicated favorable OS, but upregulated SLC39A2-5, SLC39A7, and SLC39A12-13 were associated with poor OS in the patients with breast carcinoma." (PMID 34925450, 2021).
lymph node metastasis (1 paper, 2020). "For patients with positive lymph node metastasis, SLC39A2, SLC39A3, SLC39A7, SLC39A8, SLC39A12 and SLC39A13 high expression suggested a worse OS, but SLC39A10 high expression suggested a benefit OS." (PMID 32744318, 2020). "For patients have no lymph node metastasis, high mRNA expression of SLC39A4 and SLC39A12 was also found to be correlated with worse OS." (PMID 32744318, 2020).
mental disorder (1 paper, 2016). A disease that has its basis in the disruption of mental process.
mood disorder (1 paper, 2016). A cognitive disorder a disturbance in which the person's mood is hypothesized to be the main underlying feature. "In mood disorders, there was a correlation between CNS pH and levels of SLC39A12 variants 1 and 2 mRNA." (PMID 27336053, 2016). "Compared with controls, levels of SLC39A12 variant 2 mRNA in BA 9 did not vary with diagnosis in mood disorders (KW=0.7, P=0.69)." (PMID 27336053, 2016). "Our study also shows that changes in SLC39A12 variant 1 and 2 expression have some degree of diagnostic specificity as there was no change in levels of expression of either variant of SLC39A12 in BA 9 from subjects with mood disorders." (PMID 27336053, 2016). "To better understand the significance of these data we ascertained whether SLC39A12 mRNA was altered in a number of cortical regions (Brodmann’s area (BA) 8, 9, 44) from subjects with Sz, in BA 9 from subjects with mood disorders and in rats treated with antipsychotic drugs." (PMID 27336053, 2016).
neuroblastoma (1 paper, 2014). Neuroblastoma (NB) is the most common solid, extracranial childhood tumor. "The zinc transporter ZIP12, which is encoded by the gene slc39a12, has previously been shown to be important for neuronal differentiation in mouse Neuro-2a neuroblastoma cells and primary mouse neurons and necessary for neurulation during Xenopus tropicalis embryogenesis." (PMID 25375179, 2014).
psychiatric disorder (4 papers, 2016 to 2025). A disorder characterized by behavioral and/or psychological abnormalities, often accompanied by physical symptoms. "The significant modulations of Grm1 and Slc39a12 at the proteomic level also support the biomolecular connection of bilirubin-induced damage with neuro-behavioral/psychiatric disorders that could manifest in youth and adult age." (PMID 40650037, 2025).
cancer (3 papers, 2020 to 2021). A tumor composed of atypical neoplastic, often pleomorphic cells that invade other tissues. "SLC39A12 was expressed lower in cancer sample than in normal tissue, and positively associated with a better prognosis of patients in the future." (PMID 33535184, 2021). "For patients with LUAD, mRNA levels of SLC39A1, 3, 4, 5, 6, 7, 9, 10, 11 and 14 were significant higher in cancer tissues than in relative normal samples, but SLC39A8 and SLC39A12 were expressed lower in cancer samples." (PMID 33535184, 2021).
SLC39A12 also shares sentences with these, for which no sentence is quoted: Zinc deficiency (3 papers); acrodermatitis enteropathica (1); aneurysm (1); brain diseases (1); esophageal squamous cell carcinoma (1); Infertility (1); kernicterus (1); liver cancer (1); major depressive disorder (1); male infertility (1); neurodegenerative disease (1); neurodevelopmental disorder (1); Obesity (1); ovarian carcinoma (1); serous ovarian cancer (1); Stillbirth (1); tumor (1).